ATF7-NPFF (ATF7-NPFF readthrough)
Gene: Protein-coding gene on chromosome 12 (53,506,691 to 53,625,979, reverse strand). Ensembl gene ENSG00000267281.
Genetic constraint (gnomAD): Loss-of-function variants: 17 observed, 46.76 expected, observed/expected ratio (o/e) 0.36, 90% interval 0.25 to 0.55. The upper end of that interval is the gene's LOEUF score, 0.55, which puts it in group 2 of 6, group 1 being the genes least tolerant of losing a copy. Missense variants: 457 observed, 583.37 expected, observed/expected ratio (o/e) 0.78, 90% interval 0.73 to 0.85. Synonymous variants: 191 observed, 214.19 expected, observed/expected ratio (o/e) 0.89, 90% interval 0.79 to 1.